PIWIL2 (piwi like RNA-mediated gene silencing 2)
Diseases named in the same sentence as PIWIL2 in open-access papers (continued):
Sharing a sentence is not in itself a finding about the gene and the disease.
tumor (continued). "Moreover, Piwi proteins also mediate epigenetic activation through promoting euchromatin histone modifications and piRNA transcription in subtelomeric heterochromatin in Drosophila, suggesting that Piwil2 may regulate tumor development epigenetically." (PMID 20975993, 2010). "Moreover, PL2L proteins are always co-expressed with NF-κB/RelA in the cytoplasm or nucleus, suggesting that PL2L60, in cooperation with NF-κB, may play important but opposite roles to Piwil2 in tumor development." (PMID 20975993, 2010). "The SLC39A14-PIWIL2 fusion identified in this study follows this mechanism, with the SLC39A14 promoter driving PIWIL2 overexpression, amplifying its tumor-promoting potential in HCC." (PMID 41422314, 2025). "However, downregulation of PIWIL2 in tumors was significant when the tumors were stratified by lymph node metastasis, particularly in N0 tumors compared to normal and between N0 and N2 tumors, denoting correlation of PIWIL2 both with early transformation at N0 and with tumor aggressiveness at N2." (PMID 40789164, 2025). "Several promising molecular markers with prognostic significance were also identified, including tumour HMGA2, MUC5AC/6, IDH1, PIWIL2, and DNA index." (PMID 38398089, 2024). "PIWIL2 can promote NME2 binding to the c-Myc promoter, increasing its expression, and subsequently upregulating RhoA, which can further change tumor cell invasion and migration, by modulating F-actin filaments." (PMID 39596284, 2024). "In Hela or HepG2 cells, Piwi-like RNA-mediated gene silencing 2 (PIWIL2) can upregulate c-Myc via promoting the binding of NME2 to the c-Myc promoter, inducing tumor cell proliferation." (PMID 39063217, 2024). "Emerging studies have revealed that numerous CTAs, such as SSX (CTA5), CAGE-1 (CTA3), Piwil2 (CTA80), CT45A1, and the MAGE family gene MAGE-C2 (CTA10), induce EMT to promote tumor metastasis." (PMID 35347116, 2022). "Further, it has been reported that E6 and E7 initiate the expression of Piwil2, which reactivates multiple germline factors of c-Myc, Klf4, Sox2, Nanog, and Oct4 and reprograms HR-HPV-infected cells to tumor-initiating cells (TICs)." (PMID 34257574, 2021). "It has been found that PIWI proteins in human and mice, such as PIWIL1, PIWIL2, PIWIL2 proteins, and HIWI are expressed in various types of tumor cells." (PMID 33673453, 2021). "PIWIL1, PIWIL2 and PIWIL4 were also localized within the nucleus and the cytoplasm of several subtypes of cells belonging to the tumor microenvironment such as immune cells, endothelial cells and fibroblasts." (PMID 33008024, 2020). "However, these functions of PIWIL2 in tumor development remain controversial, because most of the commercial available antibodies specific for PIWIL2 could not distinguish the full length PIWIL2 from its variants." (PMID 28545024, 2017). "Comparison with normal breast tissues revealed that two genes (PIWIL1 and PIWIL3) were up-regulated and the remaining two (PIWIL2 and PIWIL4) were down-regulated in tumor tissues." (PMID 27177224, 2016). "PIWIL2 and PIWIL4 were both expressed in all samples – both in the embryonic and the adult normal and tumor tissue." (PMID 25742785, 2015). "Both PIWIL2 and PIWIL4 were significantly downregulated in tumor tissue compared to normal tissue (p < 0.001)." (PMID 25742785, 2015). "In tumor tissue, PIWIL1 expression was detected in eleven patients (15.5%), PIWIL2 in 66 (93%), PIWIL3 in five (7%) and PIWIL4 in 60 (84.5%)." (PMID 25742785, 2015). "Both PIWIL2 and PIWIL4 were also expressed in tumor and normal tissue, indicating that the secondary pathway is not inactivated in adult tissue." (PMID 25742785, 2015). "Our current study reveals that PIWIL2 raises c-Myc expression by binding to NME2, and subsequently enhances tumor cell proliferation and F-actin filaments." (PMID 25193865, 2014).
tumor (continued). "In summary, the current study reveals that PIWIL2 interacts with NME2 and facilitates NME2 binding to G4-motif to promote c-Myc expression, contributing to tumor cell proliferation and filamentary F-actin modulation via regulating RhoA expression." (PMID 25193865, 2014). "However, the exact mechanisms PIWIL2-mediated cell transformation and tumor formation is unknown." (PMID 22110608, 2011). "Piwil2 and PL2L proteins have the potential to serve as tumor-barrier gene and tumor-initiating gene, respectively." (PMID 20975993, 2010). "The analysis of the mRNA expression levels of 21 CTAs in healthy and tumor ovarian tissue showed an up-regulation in the expression level of AKAP3, MAGEA4, PIWIL1, and PRAME in tumor samples and a down-regulation in the expression level of CTAG1A, CTAG1B, MAGEC1, and PIWIL2." (PMID 37835834, 2023). "PIWIL1, PIWIL2, PIWIL3 and PIWIL4 were all deregulated with a dissociated profile: PIWIL1 and PIWIL3 had an abnormal emergent expression and the remaining PIWIL2 and PIWIL4 were variably downregulated in tumor tissues at RNA and protein levels." (PMID 33008024, 2020). "Since we found low levels of PIWIL1 and PIWIL2 in a pancreatic normal cell line, this event seems not to be exclusive of tumor cells." (PMID 32357464, 2020). "PIWIL1 and PIWIL2 showed very scarce expression in all pancreatic cell lines, not only in the tumor-derived but also in the non-tumor cell lines." (PMID 32357464, 2020). "The transformation from the negative expression of Piwil2/Piwil4 protein in the cytoplasm to the positive expression in the nucleus indicated that the tumor became more malignant." (PMID 27894076, 2017). "Interestingly, PIWIL2 and PIWIL4 were expressed at significantly lower levels in tumor than in paired normal tissue (p < 0.001)." (PMID 25742785, 2015). "Through the study of pCSCs, we have realized that Piwil2 and PL2L proteins might play important but distinct roles from ONGs, TSGs and SGs in tumor development." (PMID 20975993, 2010). "Should the hypothesis be proven, Piwil2 and PL2L proteins not only can be used as a common biomarker for tumor but also a target for the development of new anticancer drug." (PMID 20975993, 2010). "We identified immunostaining of tumor cells with anti-PIWIL1 antibodies in 34,6% of IBCs (n = 52) and anti-PIWIL3 antibodies in 8% of IBCs (n = 12) and absence or slight staining with anti-PIWIL2 antibody in 48,3% of IBCs (n = 67) and anti-PIWIL4 antibody in 48,6% of IBCs (n = 73)." (PMID 33008024, 2020). "While full length PIWIL2 functions as an oncosuppressor promoting DNA repair and apoptosis, PL2L60 protein overexpression could promote tumorigenesis through upregulating several signal transduction pathways and inhibiting apoptotic death of tumor cells." (PMID 33008024, 2020). "By analyzing tumor microenvironment, we could observe that IBCs with PIWIL2 underexpression (but not PIWIL4 underexpression) were significantly correlated with increased immune cytotoxic CD8+ response (p = 0.000029)." (PMID 33008024, 2020). "Furthermore, PIWIL2 and MAEL are co-expressed in the stromal cells adjacent to tumor cells." (PMID 24932571, 2014). "Among others, PIWIL2 is also shown to be involved, to some extent, in TGF-beta signaling and DNA damage repair and concomitant chromatin modifications, which could also contribute to neoplasia." (PMID 25384072, 2014). "By analyzing the tumor microenvironment, we could observe that IBCs with PIWIL2 underexpression were significantly correlated with increased immune cytotoxic CD8+ response, suggesting that PIWIL2 could constitute a pertinent predictive biomarker of sensitivity to immunotherapies." (PMID 33008024, 2020).
tumor (continued). "PIWIL2/PIWIL4 co-expression and localization in HCC may be useful as an indicator for tumor prognosis, as the transformation of negative to positive cytoplasmic PIWIL2/PIWIL4 expression indicates that tumors are in the precancerous period or in the initial stage of tumorigenesis." (PMID 31399034, 2019). "Among them, PL2L60 rather than Piwil2 and other PL2L proteins is predominantly expressed in various types of human and mouse tumor cells." (PMID 20975993, 2010). "However, unlike the anchorage-independent growth phenotype, we were not able to rescue the effect of PIWIL2 depletion on proliferation, using our full length PIWIL2-FLAG construct, which actually suppressed proliferation even more, further supporting the tumor suppressing role of PIWIL2." (PMID 40789164, 2025). "Moreover, Piwil2 expression was not exclusive to HRS cells but was also detected in most of the microenvironment cells, indicating that the secondary pathway is not exclusive to tumor cells." (PMID 27329591, 2016).
colorectal (3 papers, 2020 to 2021). "A second profile of expression associated variable PIWIL2 and PIWIL4 genes downregulation, an aberrant level of PIWIL1 and absence of PIWIL3 expression observed in anal canal, head and neck, cervix, skin, kidney and pancreas tumors." (PMID 33008024, 2020). "Another study revealed that the piR-54265/PIWIL2 complex could recruit STAT3 and P-SRC via the PAZ domain of PIWIL2, form the PIWIL2/STAT3/P-SRC complex, promote STAT3 phosphorylation and signaling pathway activation, and finally contribute to colorectal tumorigenesis." (PMID 34118972, 2021).
benign tumors (2 papers, 2014 to 2020). "PIWIL1 had significantly higher expression, while PIWIL2 expression was significantly lower in cancerous tumors (early and late stage) as compared to benign tumors." (PMID 33374923, 2020). "However, the expression of PIWIL2 and PIWIL4 are significantly lower in benign tumors compared to normal ovarian tissue, suggesting an alteration of gene expression during the progression of EOC." (PMID 24932571, 2014).
infection (1 paper, 2022). The state of being infected such as from the introduction of a foreign agent such as serum, vaccine, antigenic substance or organism. "Ex/Mv from control htNSCs significantly inhibited the infection, but ablation of PIWIL2 led to a significant reduction in this antiviral effect." (PMID 34862272, 2022).
PIWIL2 also shares sentences with these, for which no sentence is quoted: adenocarcinoma (3 papers); gastric cancer (3); adenoma (2); Azoospermia (2); acute myeloid leukemia (1); arthropathy (1); autism (1); cervical (1); chronic lymphocytic leukemia (1); endometriosis (1); epithelial skin tumors (1); esophageal squamous cell carcinoma (1); female sterility (1); gynecological cancers (1); inflammatory bowel disease (1); invasive breast carcinoma (1); invasive carcinoma (1); liver diseases (1); lung squamous cell carcinoma (1); lymphoma (1); medulloblastoma (1); pancreas (1); papillary thyroid carcinoma (1); prostate (1); refractory anemia (1); rhabdomyosarcoma (1); sarcoma (1); Sertoli Cell-Only Syndrome (1); situ carcinomas (1); skin cancer (1).
A further 3 diseases each share a sentence with PIWIL2 in 1 paper.